ATG16L1 (autophagy related 16 like 1)
Diseases named in the same sentence as ATG16L1 in open-access papers (continued):
Sharing a sentence is not in itself a finding about the gene and the disease.
Salmonella Infections (14 papers, 2008 to 2025). Infections with bacteria of the genus SALMONELLA. "It has been reported that ATG16L1 conditional knockout mice exhibit defective autophagy and are more susceptible to Salmonella infection." (PMID 33505399, 2020). "Thus, we reasoned that subtle differences in ATG16L1 variant function might be revealed in Salmonella infection assays." (PMID 18852889, 2008). "Recent studies show that lysosome permeabilization induced by hydrophobic Leu-Leu-oMe (LLOMe) peptides, or disruption of vacuoles during Salmonella infection, induces ATG16L1-independent translocation of LC3 to vacuole membranes." (PMID 40458442, 2025). "Secondly, a direct interaction has recently been identified between V-ATPase and ATG16L1 during Salmonella infection, which can be inhibited by the effector protein SopF." (PMID 35511089, 2022). "The recently described v-ATPase/ATG16L1 interaction identified during Salmonella infection also depends on this domain." (PMID 34706226, 2021). "This pathway has been called the V-ATPase-ATG16L1 axis and/or VAIL for V-ATPase-ATG16L1–induced LC3B lipidation and was first identified during a study of recruitment of LC3 to vacuoles during Salmonella infection." (PMID 36288298, 2022). "To differentiate between the FIP200 and WIPI2 binding requirements for Atg12–5-16L1 recruitment to the phagophore during Salmonella infection, we transfected Atg16L1Δ/Δ MEFs with WT FLAG-Atg16L1, ERER (WIPI2-binding mutant), or DRDR (FIP200-binding mutant)." (PMID 24954904, 2014). "The molecular mechanism of ATG16L1 recruitment to these membranes is unknown, but provocatively WD40 CTD has been reported to interact with the vacuolar ATPase (v-ATPase) in the context of Salmonella infection." (PMID 34706226, 2021). "Recruitment of LC3 during Salmonella infection required the core LC3 conjugation machinery (ATG3, ATG5:ATG12, ATG7, and ATG16L1) but was independent of FIP200, suggesting a pathway similar to CASM or LAP." (PMID 36288298, 2022). "Hence, we speculated that Atg16L1 T300A would have a negative effect only on LAP or LAP-like processes, but not on canonical autophagy (including xenophagy) and that defects in LAP-like processes would be masked by canonical autophagy in Salmonella infection." (PMID 31932716, 2020).
gastric cancer (13 papers, 2020 to 2025). A primary or metastatic malignant neoplasm involving the stomach. "Different ATG16L1 SNPs have been linked to cell-derived thyroid carcinoma, colorectal cancer, gastric cancer or prostate cancer." (PMID 33147747, 2020). "In a different study, the ATG16L1 T300A is linked to better survival in gastric cancer individuals." (PMID 40534879, 2025). "The rs2241880 mutation in the autophagy-related 16-like 1 (Atg16L1) gene is associated with higher incidence of gastric cancer and H. pylori infection, which implies that defective xenophagy may be involved in the carcinogenesis of gastric cancer." (PMID 38262996, 2024). "Development of gastric cancer was associated with the ATG16L1 rs2241880 G-allele." (PMID 34965181, 2022). "Similarly, SNPs in ATG16L1 are also associated with Helicobacter pylori infection and related gastric cancer or skin conditions such as palmoplantar pustulosis and psoriasis." (PMID 33147747, 2020). "It has been reported that ATG2B, ATG5, ATG9B, ATG12, and ATG16L1 are closely related to gastric cancer (GC)." (PMID 37629426, 2023). "Reportedly, miR‐874 targets ATG16L1 in gastric cancer cells and HeLa cells." (PMID 33708385, 2021). "For instance, transfection with miR-874 mimics could sensitize gastric cancer cells to chemotherapy through regulating ATG16L1 and inhibiting autophagy." (PMID 34694211, 2021). "In short, we hypothesized that LINC00963 might be involved in promoting oxaliplatin resistance in gastric cancer by inducing autophagy through targeting of ATG16L1; further online bioinformatics tools predicted that LINC00963 regulated ATG16L1 expression by sponging miR-4458." (PMID 34697403, 2021). "In this study, it was evident that autophagic inhibition in gastric cancer improved oxaliplatin sensitivity, whereas LINC00963 knockdown induced downregulation of ATG16L1 expression, thereby improving the effects of oxaliplatin." (PMID 34697403, 2021). "According to the GEPIA database, we found that LINC00963 was aberrantly highly expressed in gastric cancer tissues and that LINC00963 expression positively correlated with ATG16L1 expression." (PMID 34697403, 2021). "This implies that the ATG16L1 T300A may have different roles in IBD and gastric cancer." (PMID 40534879, 2025).
breast carcinoma (9 papers, 2015 to 2025). "Upregulation of miR-20a strongly associates with downregulation of BECN1, SQSTM1 and ATG16L1 in human breast cancers, especially in triple-negative subtypes." (PMID 28628113, 2017). "Further experiments revealed that Rab26 mediates the autophagic degradation of phosphorylated Src through interacting with ATG16L1, consequently, resulting in the suppression of the migration and invasion ability of breast cancer cells." (PMID 33731709, 2021). "Our results demonstrated that Rab26 promotes autophagy in breast cancer cells, which probably due to enhance the recruitment of ATG16L1." (PMID 33731709, 2021). "The mRNA expression patterns of BECN1, ATG16L1 or SQSTM1 were also compared across different breast cancer subtypes." (PMID 28628113, 2017). "Treatment caused a dose-dependent increase in the total protein levels of LC3A/B, Beclin-1 (Atg6), Atg5, Atg7, and Atg16L1 in BT-474 breast cancer cells." (PMID 25580621, 2015). "A study on breast cancer cells reported a high level of miRNA-20a that increase the reactive oxygen species and increase DNA damage by targeting autophagy activating proteins, including ATG16L1." (PMID 35723373, 2022). "Finally, autophagy related protein-5 (Atg5) and autophagy-related-16 like-1 (Atg16L1) also regulate exosome biogenesis in breast cancer cells and mediate exosome secretion of prion proteins in central and peripheral neuronal cells." (PMID 33892745, 2021). "miR-20a expression correlates negatively with that of BECN1, ATG16L1 or SQSTM1 in breast cancer." (PMID 28628113, 2017). "At the same time, by interacting with autophagy-related 16-like 1 (ATG16L1), RAB26 directs synaptic vesicles to undergo autophagy and inhibits migration and invasion of invasive breast cancer cells." (PMID 40821113, 2025). "Compared with the normal mammary tissues, breast cancer tissues showed an obvious reduction in BECN1, ATG16L1 and SQSTM1 levels, whereas OPTN expression was higher in cancer tissues." (PMID 28628113, 2017). "Our findings demonstrated that Rab26 harnesses the same mechanism as that in non-cancer cells to regulate migration and invasion of breast cancer cells, in that Rab26 promotes the autophagic targeting and degradation of p-Src through interacting with ATG16L1." (PMID 33731709, 2021).
colon cancer (9 papers, 2018 to 2026). "ATG16L1 deficiency enhances programmed cell death of colon cancer organoids induced by IFN-γ and TNF, thus increasing their sensitivity to host immunity." (PMID 37741832, 2023). "We engineered ATG16L1‐deficient clones of the human colon cancer cell line HCT116 and the human breast epithelial cell line MCF10A using CRISPR/Cas9." (PMID 29317426, 2018). "Although differences in the colon were less pronounced, we also noted colonic tumors in aged Atg16l1/Xbp1/Rnaseh2bΔIEC mice (20.0%), when compared to aged Xbp1/Rnaseh2bΔIEC mice (2.13%)." (PMID 41057521, 2025). "Increased prevalence of small intestinal and colonic tumors resulted in decreased survival of Atg16l1/Xbp1/Rnaseh2bΔIEC mice." (PMID 41057521, 2025). "Deletion of Atg16l1 in engineered murine colon cancer organoids inhibits tumor growth in primary (colon) and metastatic (liver and lung) niches in syngeneic female hosts, primarily due to increased sensitivity to IFN-γ-mediated immune pressure." (PMID 37741832, 2023). "Treatment of HCT116 ATG16L1 T300 colon cancer cells with AR12 or neratinib increased the activities of the AMPK, ULK1 and ATG13." (PMID 34252884, 2021). "HCT116 ATG16L1 T300 colon cancer cells and GBM6 cells, a PDX glioblastoma isolate expressing truncated EGFR vIII, were transfected with a plasmid to express LC3-GFP-RFP and with siRNA molecules to knock down expression of AMPKα1 or eIF2α." (PMID 34252884, 2021).
psoriasis (9 papers, 2017 to 2025). An autoimmune condition characterized by red, well-delineated plaques with silvery scales that are usually on the extensor surfaces and scalp. "In psoriasis, autophagy has been implicated in disease pathogenesis, specifically through polymorphisms in the ATG16L1 gene, which also have a significant role in epidermal keratinization." (PMID 40565008, 2025). "One of the earliest studies of autophagy in psoriasis revealed that a polymorphism in the autophagy gene ATG16L1 can be used to predict the likelihood of acquiring psoriasis." (PMID 35370701, 2022). "A recent study reported that single-nucleotide polymorphisms (SNPs) in the ATG16L1 gene (rs10210302, rs12994971, rs2241880, rs2241879, and rs13005285) are linked to psoriasis susceptibility." (PMID 32235789, 2020). "Genetic screening of psoriasis patients of Estonian origin reveals several single-nucleotide polymorphisms (SNPs) associated with ATG16L1, though the functional role of ATG16L1 variants in skin biology is unclear." (PMID 29988591, 2018). "Among ATG16L1 genetic polymorphisms, rs10210302 and rs2241880 were implicated in patients’ predisposition to Paget bone disease, psoriasis and Crohn’s diseases." (PMID 28839236, 2017). "Furthermore, single nucleotide polymorphisms (SNP) in ATG16L1 have been linked to the risk of psoriasis." (PMID 38704587, 2024). "Moreover, genetic polymorphisms in the autophagy gene ATG16L1 contribute to the risk of psoriasis, and impaired autophagy due to lysosomal dysfunction is observed in chronic atopic dermatitis and psoriasis lesions." (PMID 38704587, 2024). "Moreover, a recent study revealed that several single nucleotide polymorphisms in the ATG16L1 gene are linked with susceptibility to the development of psoriasis." (PMID 32461989, 2020). "In addition, mutation of the psoriasis risk gene AP1S3 has been found to result in impaired autophagy and increased skin inflammation, and increased expression of ATG16L1 has been observed in DCs from psoriatic arthritic patients." (PMID 30108582, 2018). "There is no direct evidence to show whether ATG16L1 contributes to psoriasis." (PMID 30108582, 2018).
viral infection (9 papers, 2011 to 2025). "Additionally, host genetic factors, such as mutations in ATG16L1 associated with CD, can interact with viral infections like norovirus to exacerbate pathological conditions." (PMID 41170430, 2025). "Virus infection increased the protein levels of the autophagy markers ATG16L1 and Beclin-1 and the autophagy regulator mTOR." (PMID 23924832, 2013). "Overall, we present evidence that regulation of lipid transport by the WD domain of ATG16L1 may have downstream implications in attenuating viral infection and limiting lethal cytokine signaling." (PMID 40143422, 2025). "However, key autophagy genes including ATG1, ATG3, ATG9, ATG12, and ATG16L1 were significantly upregulated in horses after viral infection." (PMID 39287214, 2024). "This hypothesis is consistent with the opposing roles of Nod2 and Atg16L1 downstream of viral infection." (PMID 21994779, 2011).
hepatocellular carcinoma (8 papers, 2018 to 2025). A malignant tumor that arises from hepatocytes. "The most important polymorphisms in hepatocellular carcinoma were rs2241880 in ATG16L1, rs77859116, rs510432, and rs548234 in ATG5." (PMID 38353395, 2024). "We next performed side-by-side experiments comparing the changes in cell signaling caused by regorafenib, aramchol and the drugs combined in ATG16L1 T300/T300 and ATG16L1 A300/A300 HCT116 colorectal cancer cells and in HuH7 hepatoma cells." (PMID 40827882, 2025). "IGF2BP1 can recognize circMDK via m6A sites, activate the PI3K/AKT/mTOR signaling pathway through the miR-346/874-3p-ATG16L1 axis, and ultimately promote the proliferation, migration and invasion of hepatoma cells." (PMID 39229278, 2024). "The current study aims to examine the protective action of C3G against hepatocellular carcinoma through the investigation of the autophagy protein ATG16L1 expression along with its related RNA molecules (hsa_circ_0001345 and miRNA106b) in Wistar rats." (PMID 35723373, 2022). "MiR-142-3p reduced sorafenib-induced autophagy through the downregulation of ATG5/ATG16L1 in hepatocellular carcinoma cells." (PMID 33082306, 2020). "In conclusion, our study determined the prognostic and immunological roles of necroptosis‐related molecules such as TRAF2, PGAM5, ATG16L1, CADR9, PCYT1A, PARP2 and TLR2 in hepatocellular carcinoma." (PMID 35293027, 2022).
ileitis (8 papers, 2015 to 2025). "In mouse models, decreased expression levels of Atg5, Atg7, or Atg4B generated abnormal Paneth cell functions, and in CD-like ileitis, deficiency of Atg16L1 also altered Paneth cell morphology." (PMID 35408838, 2022). "One example of this susceptibility gene-microbial interaction in mice is that a combination of impaired autophagy (from a mutated Atg16L1) and colonization of murine norovirus results in Paneth cell dysfunction, resembling the abnormalities seen in some patients with Crohn's ileitis." (PMID 30026758, 2018). "Complete knockout of Atg3, Atg5, Atg7, or Atg16L1 is lethal in mice, and impairment of either Atg7 or Atg16L1 results in severe CD-like transmural ileitis." (PMID 35408838, 2022). "Loss of the autophagy-related gene Atg16l1 inhibited the degradation of TRIF mediated by autophagy receptors SQSTM1 and Tax1BP1, thus driving TRIF-dependent inflammatory signaling in S. Typhimurium-induced ileitis." (PMID 39809743, 2025). "Interestingly, spontaneous ileitis observed in Xbp1ΔIEC mice is converted into severe CD-like transmural ileitis when both mechanisms, ER stress and autophagy, are compromised (Atg7/Xbp1ΔIEC and Atg16L1/Xbp1ΔIEC double transgenic mice)." (PMID 26221063, 2015). "Dysfunctions in either unfolded protein response factor, X‐box binding protein 1 (XBP1), or autophagy (ATG16L1 or ATG7) in IECs result in the reciprocal compensatory, and severe spontaneous ileitis develops if both mechanisms are defective." (PMID 29941542, 2018).
ulcerative colitis (8 papers, 2009 to 2025). An inflammatory bowel disease involving the mucosal surface of the large intestine and rectum. "Thus, polymorphisms in genes, such as NOD2/CAR15, ATG16L1, IL23R, and IL10R have been involved in susceptibility to pIBD or to very-early-onset ulcerative colitis." (PMID 32397546, 2020).
Alzheimer disease (7 papers, 2021 to 2025). A progressive, neurodegenerative disease characterized by loss of function and death of nerve cells in several areas of the brain leading to loss of cognitive function such as memory and language. "As African-Americans trend to present with a more rapid onset and severe Alzheimer’s disease when compared to European Americans, we postulate that ATG16L1 isoform expression may play a role." (PMID 34252884, 2021). "Furthermore, WDR domain-deficient mice exhibited Alzheimer’s disease (AD) phenotypes, indicating that canonical autophagy might be somewhat blocked when cells were deprived of the WDR domain of ATG16L1." (PMID 38674078, 2024). "The aim of this study was to further investigate the role of genes identified in our previous studies as relevant for the pathophysiology of Alzheimer’s disease and T2DM comorbidity, namely ATG16L1, ATG16L2, GABARAP, GABARAPL1, GABARAPL2, and SQSTM1." (PMID 36901549, 2023). "This suggests that the interaction between ATG16L1 and STING may influence various diseases, including inflammation, cancer and Alzheimer's disease." (PMID 40211890, 2025).
atherosclerosis (7 papers, 2016 to 2024). A disease characterized by the build-up of fatty material and calcium deposition in the arterial wall resulting in partial or complete occlusion of the arterial lumen. "Analysis of atherosclerosis on aortic root cross-sections showed that treatment with anti-CD25 completely abrogated the atheroprotective effect associated with Atg16l1 deficiency in DCs." (PMID 31610723, 2019). "Atg16l1 deficiency in DCs prevents experimental atherosclerosis in a regulatory T-cell (Treg)–dependent manner." (PMID 31610723, 2019). "Disruption of autophagy by deleting autophagy-related 16-like 1 (Atg16l1) has been shown to limit the extent of atherosclerosis and influence plaque phenotype, such as reducing the necrotic core area." (PMID 38397127, 2024). "The expression of ATG16L1 enhances the autophagy of macrophages and has been shown to prevent atherosclerosis." (PMID 34220924, 2021). "Previous studies have demonstrated that the expression of ATG16L1 in atherosclerosis is closely related to the instability of lesions on atherosclerotic plaques." (PMID 34220924, 2021). "Furthermore, they also observed a dose-dependent inhibition of the expression of ATG16L1, decreasing ATG16L1-induced autophagy and activating NLRP3 inflammasome, which has been recently found to be critical for the development of atherosclerosis and has been also linked to AD." (PMID 30275434, 2018). "Although there have been some studies and reports on ATG16L1 in the context of immunity, atherosclerosis, and cardiomyocytes, there has been no work on the role of the ATG16L1 gene in the occurrence and development of CAD or AMI." (PMID 34220924, 2021). "Interestingly, this pathway seems to have different roles in different DC subtypes, as deletion of Atg16l1 in CD8α+ DCs did not affect the development of atherosclerosis compared to CD11b+ DCs." (PMID 38397127, 2024). "However, Atg16l1 deletion in our model did not affect DC numbers, and none of those genes was significantly altered by Atg16l1 deletion in DCs within the context of HFD-induced atherosclerosis." (PMID 31610723, 2019).
colorectal cancer (7 papers, 2019 to 2025). A primary or metastatic malignant neoplasm that affects the colon or rectum. "On the other hand, in 2017, a study showed that ATG16L1 rs2241880 was linked to a decrease in metastasis in patients with colorectal cancer." (PMID 38353395, 2024). "Deficiency of ATG16L1 can provoke activation of IL-1β and IL-18 and is associated with an elevated risk of colorectal cancers." (PMID 33171939, 2020). "Thus, colorectal cancers with high expression of ATG16L1 were associated with poor clinical outcomes under PD-L1 therapy." (PMID 41057521, 2025). "Analysis of Kaplan–Meier curves showed that low ATG16L1 expression is prognostic for improved overall survival in patients with lung and clear cell renal cancer and improved relapse-free survival in patients with colorectal cancer." (PMID 30736412, 2019). "Similarly, mutations in different autophagy related genes (ATG5, ATG2B, ATG16L1, and ATG9B) were observed in hepatocellular carcinoma and gastric and colorectal cancers." (PMID 33171939, 2020).